NDUFA7 (NADH:ubiquinone oxidoreductase subunit A7)
Description:
Accessory subunit of the mitochondrial membrane respiratory chain NADH dehydrogenase (Complex I), that is believed not to be involved in catalysis. Complex I functions in the transfer of electrons from NADH to the respiratory chain. The immediate electron acceptor for the enzyme is believed to be ubiquinone.
Synonyms: CI-B14.5a; B14.5a
Tractability: Small molecule: an approved drug acts on it; a structure with a bound ligand is known. Antibody: UniProt places it where antibodies can reach, with high confidence. PROTAC: ubiquitination databases record sites on it; its protein half-life has been measured.
Gene: Protein-coding gene on chromosome 19 (8,308,768 to 8,321,382, reverse strand). Ensembl gene ENSG00000267855.
Subcellular location: Mitochondrion inner membrane
Subcellular location (Human Protein Atlas): Mitochondria
Pathways (Reactome):
Metabolism: Complex I biogenesis; Respiratory electron transport
Gene Ontology:
Molecular function: protein binding; NADH dehydrogenase (ubiquinone) activity
Biological process: aerobic respiration; mitochondrial electron transport, NADH to ubiquinone; proton motive force-driven mitochondrial ATP synthesis; ATP synthesis coupled electron transport; proton transmembrane transport
Cellular component: mitochondrial inner membrane; mitochondrion; respiratory chain complex I
Genetic constraint (gnomAD): Loss-of-function variants: 19 observed, 13.47 expected, observed/expected ratio (o/e) 1.41, 90% interval 0.97 to 1.89. The upper end of that interval is the gene's LOEUF score, 1.89, which puts it in group 6 of 6, group 1 being the genes least tolerant of losing a copy. Missense variants: 155 observed, 134.29 expected, observed/expected ratio (o/e) 1.15, 90% interval 1.01 to 1.32. Synonymous variants: 70 observed, 54.72 expected, observed/expected ratio (o/e) 1.28, 90% interval 1.05 to 1.56.
Homologues: Orthologues: chimpanzee NDUFA7 (100% identical), mouse Ndufa7 (91% identical), pig NDUFA7 (90% identical), rabbit NDUFA7 (88% identical), dog NDUFA7 (86% identical), guinea pig NDUFA7 (85% identical), tropical clawed frog NDUFA7 (62% identical), zebrafish ndufa7 (59% identical), Drosophila melanogaster ND-B14.5A (38% identical), Caenorhabditis elegans ndua-7 (35% identical), Drosophila melanogaster ND-B14.5AL (34% identical).
Diseases named in the same sentence as NDUFA7 in open-access papers:
NDUFA7 is named in the same sentence as 24 diseases in open-access papers, as found by Europe PMC text mining. Sharing a sentence is not in itself a finding about the gene and the disease. The quoted sentences say what the papers report.
cardiac hypertrophy (4 papers, 2020 to 2025). "NDUFA7 has been confirmed to be associated with pathological cardiac hypertrophy, but research on tumor occurrence and development remains limited." (PMID 41364140, 2025). "NDUFA7 is highly expressed in the heart and its levels experience a marked decrease in a mouse model of myocardial hypertrophy." (PMID 41364140, 2025). "The biological function of NDUFA7 has recently been uncovered in a study that showed that NDUFA7 knockout led to cardiac hypertrophy, indicating that depletion of NDUFA7 resulted in increased production of reactive oxygen species and calcineurin signalling." (PMID 36499081, 2022). "In this study, we found that NDUFA7 exhibited high expression in the heart, and its level was significantly decreased in mice model of cardiac hypertrophy." (PMID 32989924, 2020). "We further examined expression of cardiac hypertrophy markers by qPCR analysis and found that NDUFA7 inhibition markedly increase the mRNA level of ANP and BNP, indicating that depletion of NDUFA7 leads to cardiac hypertrophy." (PMID 32989924, 2020). "For instance, the downregulation of Ndufa7 found by us (x = −1.92 in the untreated CCC and x = −1.72 in untreated IHF) was also reported in cardiac hypertrophy." (PMID 41296444, 2025).
Huntington disease (3 papers, 2012 to 2022). Huntington disease (HD) is a rare neurodegenerative disorder of the central nervous system characterized by unwanted choreatic movements, behavioral and psychiatric disturbances and dementia. "For example: Huntington’s disease (NDUFA7, NDUFC1, NDUFB2, NDUFB3, NDUFA8), atrophy of optic nerve (NDUFS4) and Leigh syndrome (NDUFS7, NDUFA2, NDUFS4)." (PMID 23028713, 2012).
Parkinson disease (3 papers, 2016 to 2022). A progressive degenerative disorder of the central nervous system characterized by loss of dopamine producing neurons in the substantia nigra and the presence of Lewy bodies in the substantia nigra and locus coeruleus. "This analysis revealed that the genes implicated in Parkinson’s disease (Atp5a1, Ndufa7, Ndufb2, Ndufs8, Park7, Cox7a2, Cox7c, Cox6b1, Cycs, Uchl1) were upregulated in thia-exposed mice (p-value = 4.2E-3)." (PMID 34295895, 2021).
breast carcinoma (2 papers, 2023 to 2025). "For example, multiple Complex I subunits, such as NDUFB1, NDUFS4, NUBPL, and NDUFA7, have been implicated in the metabolic plasticity of breast cancer cells." (PMID 41157129, 2025).
rheumatoid arthritis (2 papers, 2020 to 2022). A chronic, systemic autoimmune disorder characterized by inflammation in the synovial membranes and articular surfaces. "NDUFA7 has also been associated with the development of rheumatoid arthritis, which was suggested to be mechanistically driven by reactive oxygen species." (PMID 36499081, 2022). "It has been reported that an association is observed between NDUFA7 and rheumatoid arthritis (RA) with severe erosive arthritis." (PMID 32989924, 2020). "NDUFA7 has been reported to be associated with rheumatoid arthritis (RA) with severe erosive arthritis." (PMID 32989924, 2020). "In a recent study, it is indicated that ROS might involve in the NDUFA7 induced rheumatoid arthritis." (PMID 32989924, 2020).
breast tumours (1 paper, 2023). "Therefore, we analysed the expression of 6 genes from the OXPHOS signature (AIFM1, NDUFV1, NDUFAB1, NDUFA7, NDUFS6 and MRPS12) among the most enriched in metastatic samples, by RT-PCR in specimens of 503 breast tumours patients with a follow-up of 20 years." (PMID 37452026, 2023).
Cognitive impairment (1 paper, 2024). Abnormal cognition is characterized by deficits in thinking, reasoning, or remembering. "In participants with cognitive impairment, the expression levels of KEGG:M00146’s NDUFA2, NDUFA3, NDUFA4, NDUFA6, NDUFA7, NDUFA10, and NDUFA12 increased, but the expression levels of NDUFA5, NDUFA4L2, and NDUFAB1 marginally decreased." (PMID 38542318, 2024).
colorectal cancer (1 paper, 2024). A primary or metastatic malignant neoplasm that affects the colon or rectum. "Furthermore, OMe-Ph-Elemene suppressed colorectal cancer cells’ mitochondrial oxidative phosphorylation by downregulating NDUFA7." (PMID 39765827, 2024).
melanoma (1 paper, 2025). A malignant, usually aggressive tumor composed of atypical, neoplastic melanocytes. "RT‐PCR analysis of melanoma cell lines A375 and A375 MEK after treatment with IC50 concentrations of KU757 confirmed the downregulation of CD20, CD25 and NDUFA7, as well as the upregulation of PRKCH, BMP2 and ADAMTS9 hub genes (p < 0.05)." (PMID 40135438, 2025).
tumor (4 papers, 2019 to 2025). "Similarly, NDUFA7, an accessory subunit of Complex I, has not been directly implicated in tumor biology." (PMID 41157129, 2025).
cancer (3 papers, 2014 to 2024). A tumor composed of atypical neoplastic, often pleomorphic cells that invade other tissues. "As in NAT10 KD cells, the Remodelin-treated cancer cells showed a remarkable decrease in the mitochondrial respiratory genes NDUFAB1, NDUFA3, and NDUFA7." (PMID 37237981, 2023).
cardiac diseases (1 paper, 2020). "We then searched the GEO (gene expression omnibus) database to explore whether NDUFA7 is involved in cardiac diseases." (PMID 32989924, 2020). "However, the biological role of NDUFA7 in cardiac diseases has not been explored." (PMID 32989924, 2020).
immune diseases (1 paper, 2024). "In addition, genes related to immune diseases (e.g., BID, SMARCD3, ATP6V1E1, NFKB2), energy metabolism (e.g., HAO1, NDUFA7, CERS4, MTHFD1), and other factors were also screened." (PMID 38750582, 2024).
metabolic disorders (1 paper, 2025). "Ndufa7 is the NADH; ubiquinone oxidoreductase subunit A7 in complex I of the mitochondrial electron transport chain (ETC), whereby its dysregulated expression may underlie metabolic disorders during AD." (PMID 40979532, 2025).
neurodegenerative disease (1 paper, 2019). A disorder of the central nervous system characterized by gradual and progressive loss of neural tissue and neurologic function. "Multiple pathways involved in neurodegenerative diseases and oxidative phosphorylation were enriched in TPLB versus OVX groups, with the regulation of several mitochondrial proteins with gene names of Ndufa7, Uqcr10, and ATP8." (PMID 31428228, 2019).
NDUFA7 also shares sentences with these, for which no sentence is quoted: Alzheimer disease (2 papers); COVID-19 (1); depressive disorder (1); Leigh syndrome (1); leukemia (1); lung adenocarcinoma (1); lung carcinoma (1); non-alcoholic fatty liver disease (1); viral infection (1).